Y_RNA (Y RNA )
Gene: Miscellaneous RNA gene on chromosome 14 (66,177,527 to 66,177,635, reverse strand). Ensembl gene ENSG00000200860.
Homologues: Orthologues: chimpanzee Y_RNA (100% identical), macaque Y_RNA (96% identical). Paralogues in human: Y_RNA (84% identical), RNY1P5 (83% identical), Y_RNA (83% identical), Y_RNA (82% identical), Y_RNA (81% identical), Y_RNA (80% identical), Y_RNA (79% identical), Y_RNA (78% identical), Y_RNA (77% identical), RNY1 (76% identical), Y_RNA (76% identical), Y_RNA (75% identical), and 95 more.